SP1 (Sp1 transcription factor)
Diseases named in the same sentence as SP1 in open-access papers (continued):
Sharing a sentence is not in itself a finding about the gene and the disease.
cancer (continued). "Therefore, we tested if the parallel association between Sp1 and SENP3 levels in an in vitro cell system reflects the situation in cancer cells and patient-derived tissues." (PMID 26511642, 2016). "Our results clearly demonstrate for the first time that not only Sp1 but also Sp3 and Sp4 play a role in cancer cell growth, survival and migration/invasion of multiple cancer cell lines and regulate expression of gene products consistent with these observations." (PMID 26967243, 2016). "SP1 controls the transcription of multiple genes, many of which have been described as promoting the ‘hallmarks’ of cancer: proliferation, independence from growth signals, avoidance of apoptosis and immune destruction, invasion and metastasis, and angiogenesis." (PMID 27144453, 2016). "Some of the differences between studies may be due to the methods used to modulate Sp expression since overexpression of Sp1 and Sp3 in some cancer cell lines induces apoptosis and inhibits growth." (PMID 26967243, 2016). "In this study, we identified Sp1 as the TF to activate TIAM2S expression in these cancer cells." (PMID 26763486, 2016). "Specificity protein 1 (Sp1) is a ubiquitous zinc-finger transcription factor that binds guanine–cytosine-rich elements in the promoter region of its target genes, and upregulates the expression of various important genes for cancer initiation and progression." (PMID 27738323, 2016). "Since PLD1 was also reported as an oncogenic gene in various human cancers, we boldly postulated that it positive correlated with Sp1, and they could promote PDAC progression synergistically." (PMID 27713167, 2016). "The aberrant expression of Sp1 contributes to the tumorigenesis of various types of cancer." (PMID 26763486, 2016). "Our findings provide a new explanation for the enrichment of Sp1 protein in cancers and suggest a global regulation of SUMO2/3 conjugated proteins whose levels may be tightly controlled by SENP3 and RNF4." (PMID 26511642, 2016). "In many cancers, Sp1 is overexpressed and levels correlate with tumor stage and poor prognosis." (PMID 27109240, 2016). "The Sp1-target genes involve into the hallmarks of cancer, which both activates and suppresses the expression of genes including prominent oncogenes and tumor suppressors, as well as genes involved in important biological processes in cell growth and differentiation." (PMID 27829234, 2016). "In telomerase-positive cells, particularly cancer cells, Sp1 may activate hTERT expression on its own or in conjunction with specific co-activators." (PMID 27548225, 2016). "Sp1 also participates in cancer development and progression." (PMID 27057625, 2016). "Further studies are required to determine whether this cooperation between Sp1 and Myc also functions to regulate the expression of other oncogenic genes in cancer." (PMID 25890196, 2015). "In conclusion, Sp1 driven up-regulation of miR-19a promotes cancer by targeting RHOB." (PMID 26041879, 2015). "SP1, a well-known ubiquitous transcription factor, is highly expressed in many types of malignancies and plays an important role in progression and metastasis of cancer through binding to GC-rich sequences, thereby regulating various downstream genes." (PMID 26362062, 2015). "Thus, in addition to increased protein level via inhibition of proteasomal degradation, HIF-1α expression can be regulated at the transcriptional level via direct or indirect interaction of Sp1 with the HIF1A promoter region in cancer cells." (PMID 26703734, 2015). "Post-transcriptional modifications other than phosphorylation may enhance the activity of Sp1 in cancer cells exposed to hypoxia." (PMID 26703734, 2015).
cancer (continued). "Furthermore, it was reported that negative regulation of the HIF1A gene by protein arginine methyltransferase 1 in cancer cells involves altered Sp1 protein expression level." (PMID 26703734, 2015). "Reported targets of miR-330-3p in various cancer types include Sp1, CDC42 and E2F1." (PMID 26221725, 2015). "So far, it is unclear whether these types of Sp1 activation occur and perform any function in cancer cells." (PMID 26703734, 2015). "Pharmacologic inhibition of Sp1-driven induction of the VEGF gene under hypoxia may increase the radiosensitivity of cancer tissues." (PMID 26703734, 2015). "However, in contrast to HRE-dependent mechanisms, how and to what extent these Sp1-dependent mechanisms contribute to hypoxia-driven gene transcription in cancer cells is not fully understood." (PMID 26703734, 2015). "In addition, HIF-2α binding collaborates with proximal Sp1 to induce gene expression in normal and cancer cells." (PMID 26703734, 2015). "Such modulated Sp1 may play roles in gene expression required for the expression of malignant phenotypes in cancer cells." (PMID 26703734, 2015). "Sp1 also regulates cancer cell metabolism by regulating a number of metabolic genes in cancers." (PMID 25923237, 2015). "Studies in this laboratory have demonstrated that basal expression of genes, such as survivin, VEGF and EGFR, in various cancer cell lines is dependent on specificity protein (Sp) transcription factors Sp1, Sp3 and Sp4 which are highly expressed in many cancer cells and tumors." (PMID 26673922, 2015). "The functional importance of Sp1, Sp3 and Sp4 in cancer cells has been confirmed by RNA interference (RNAi) showing that knockdown of Sp transcription factors Sp1, Sp3 and Sp4 (singly or combined) decreases cell proliferation, survival, angiogenesis and inflammation." (PMID 26673922, 2015). "Thus, Sp1-mediated overexpression of the wild-type IDH2 gene in response to hypoxia potentially contributes to the radioresistance of cancer cells." (PMID 26703734, 2015). "Sp1 binds to GC-rich motifs of promoters and regulates genes involved in tumour growth, apoptosis and angiogenesis; thus, the functional status of Sp1 may affect the therapeutic response of anti-angiogenic strategies for human cancers." (PMID 25598321, 2015). "Importantly, Sp1 is elevated in many cancers and studies using LNCaP cells show that this leads to increased AR transcription." (PMID 26448047, 2015). "Cell proliferation and flow cytometric analysis showed that si-Sp1 could inhibit BC cell growth, increase cancer cell apoptosis, affect cell cycle, which resembled the inhibitory effects of miR-200b on the BC cell." (PMID 25639535, 2015). "Therefore, investigation on Sp1 holds great promise to provide insight into related carcinogenesis and to develop efficient therapeutic strategies for related cancers." (PMID 24728382, 2014). "Therefore, it seems to be important that the suppression of SP1 itself, as well as the inhibition of the posttranslational modifications of SP1, are critical for cancer therapy." (PMID 25060396, 2014). "Given that Sp1 is overexpressed in cancer cells, its diminished levels upon treatments with DIG-MSK may result in tumor remission." (PMID 25110883, 2014). "Therefore, it would be worthwhile to test promising cancer therapeutic drugs targeting Sp1 with less cytotoxic potency." (PMID 25418289, 2014). "Previous studies indicated that Sp1 accumulates in most types of cancer cells." (PMID 25398907, 2014). "Therefore, the complete phosphorylation of Sp1 is essential for cell cycle progression of cancer cells." (PMID 25398907, 2014). "Moreover, we found that the cancer cell lines (A549 and H1299) had the strong binding activity of Sp1 on hTERT promoter by comparison with the normal cell lines (HLF)." (PMID 25294805, 2014).
cancer (continued). "Furthermore, Sp1 is highly expressed in various cancers such as breast carcinoma, thyroid cancer, hepatocellular carcinoma, pancreatic cancer, colorectal cancer, gastric cancer, cervical cancer and lung cancer." (PMID 24423061, 2014). "Interestingly, both Mcl-1 and survivin share transcriptional regulation by SP1, providing an additional molecular basis for the dual suppression of these critical pro-survival factors in cancer cells." (PMID 25296978, 2014). "Kras activation and the Notch pathway might activate ERK1/2 to phosphorylate Sp1, thus stabilizing Sp1 in the early stages of cancer." (PMID 24519909, 2014). "To determine whether CBP can acetylate transactivators bound to hTERT promoter, we immunoprecipitated the nuclear extracts from lung normal and cancer cell lines using anti-Sp1 antibody." (PMID 25294805, 2014). "In addition to being as an oncogene, Sp1 can also act as a tumor suppressor in various types of cancer." (PMID 25099028, 2014). "Thus, from the investigation of five cell lines, we concluded that hCtr1 and Sp1 are coordinately upregulated by cisplatin in human cancer cells." (PMID 24132751, 2014). "However, positive staining of EGFR and Fascin was apparent only in basal layer of epithelium tissue adjacent to carcinoma, while p-Sp1 was weak staining in higher granular layer of the epithelium." (PMID 25153136, 2014). "SP1 is a widely described gene involving in tumorigenesis, cancer metastasis and proliferation." (PMID 24180482, 2013). "In addition, Sp1 is overexpressed in several cancers and is closely correlated with the prognosis of patients." (PMID 23403540, 2013). "Given that Mina is aberrantly expressed in many cancers, it is tempting to speculate that its transcriptional regulation by Sp1/3 may contribute to its roles in cell proliferation and oncogenesis." (PMID 24324617, 2013). "Transcriptional activators such as Sp1, nuclear factor-Y and β-catenin/T cell factor (TCF) have been implicated in the activation of human PTTG1 expression via the regulation of its promoter activity in various cancer cells." (PMID 23977008, 2013). "Suppression of SP-1 has been effective in the prevention and treatment of cancer." (PMID 23437203, 2013). "Human Sp1 expression construct was established and transfected into cancer cells." (PMID 23394613, 2013). "SP1 expression therefore increases as normal gastric tissues develop into cancer." (PMID 23437057, 2013). "However, as the transformation progressed from intestinal metaplasia to low- and high-grade dysplasia, SP1 expression increased markedly and became high in carcinoma." (PMID 23437057, 2013). "Sp1 accumulates in most of cancer types and participates in their tumorigenesis." (PMID 23148884, 2012). "Regarding to the cancer-related functions, In this study, suppression of Sp1 protein level followed by induction of MSTO-211H cell apoptosis by cafestol and kahweol were investigated in oreder to determine Sp1's potential as a significant target for human MPM therapy as well." (PMID 22734486, 2012). "The involvement of Sp1 in the development of various cancer types is well known." (PMID 23148884, 2012). "Additionally, Sp1 is highly expressed in various cancers such as breast carcinoma, thyroid cancer, hepatocellular carcinoma, pancreatic cancer, colorectal cancer, gastric cancer, and lung cancer." (PMID 22734486, 2012).
cancer (continued). "Our results demonstrate Sp1 as an efficient therapeutic target of cancer." (PMID 22734486, 2012). "Both 14-3-3zeta and SP1 genes have been shown to participate in cancer development and progression." (PMID 22606351, 2012). "Dysregulation of Sp1 is observed in many cancers and neurodegenerative disorders." (PMID 23148884, 2012). "Our ongoing studies are testing the hypothesis raised - that Sp1-HDAC interaction may be central to the cancer preventive actions of butyrate through engagement of specific target genes - in cross sectional studies involving human volunteers." (PMID 20950428, 2010). "Low levels of butyrate, as may be the case in cancer-prone low-fibre consumers, would result in lower levels of Sp1 acetylation, resulting in less cell death and more proliferating cells in the colon as a consequence of reduced Bak and p21 expression." (PMID 20950428, 2010). "Sp1 is a ubiquitous transcription factor and Sp1-regulated genes include those involved in cell cycle regulation, apoptosis and lipogenesis: all major pathways in cancer development." (PMID 20950428, 2010). "Secondly, we found that THL could inhibit, in cancer cells, the activity of ERK1/2, which phosphorylates the transcription factor Sp1 and causes the recruitment of Sp1 to the vegf-A promoter." (PMID 20429953, 2010). "Sp1 is a common element in cancer-specific promoters, for example CEA, survivin and hTERT." (PMID 17687334, 2007). "Alternatively, assessment of Sp1/Sp3 ratios in cancer cells may provide an additional prognostic marker for treatment with drugs like doxorubicin that cause cell cycle arrest." (PMID 17511886, 2007). "Gene Ontology (GO) and Kyoto Encyclopedia of Genes and Genomes (KEGG) analysis of the SP1‐related peaks revealed relevant enrichment of the ErbB signaling pathway, FoxO signaling pathway, establishment or maintenance of cell polarity, and several cancer‐related pathways." (PMID 40056047, 2025). "Furthermore, ACSS2 serves a dual function during acidosis by facilitating histone acetylation in cancer cells and enhancing the stability of the transcription factor SP1, which synergize to commence metabolic reprogramming under acidosis through the regulation of SAT1." (PMID 38429478, 2024). "It has been documented that SP1 could regulate METTL1 expression in cancer cells." (PMID 38977661, 2024). "Inhibiting Sp1 may represent a plausible therapeutic target in mouse models of LN, as the new Sp1 mithralog inhibitor EC-8042 shows pleiotropic activities and less toxicity in cancer treatment." (PMID 38256157, 2024). "Therefore, we hypothesized that macrophages promoted the acquisition of cancer stem-like properties leading to GR in PAAD via the Sp1/CD44 axis." (PMID 37553567, 2023). "Moreover, Sp1 regulates the DNA damage response, cell apoptosis, cell senescence, the ability to escape from immune system, and tumor angiogenesis, which leads to the cancer drug resistance." (PMID 35337344, 2022). "Therefore, Sp1 is an attractive target of cancer treatment in PCa patients." (PMID 35163245, 2022). "Therefore, reducing the expression of SP1 should permit control of cancers." (PMID 34199886, 2021). "Interestingly, targeting Sp1 has demonstrated prior success in cancer cell lines." (PMID 33445667, 2021).
cancer (continued). "DcR3 expression was also significantly higher in SCLC cancer tissues compared to normal lung tissue, thus inhibition of DcR3 expression by interfering with upstream Sp1 pathway may provide a novel immunotherapeutic target to restore antitumor immune response in low‐risk group SCLC patients." (PMID 34741430, 2021). "In addition, SP-1 has also been indicated to possess anti-cancer activity against various cancers." (PMID 34572295, 2021). "Therefore, studies have addressed the possibility of targeting Sp1 to treat cancer cells." (PMID 33329003, 2020). "Therefore, miR‐326 plays a key role in the cancer‐promoting effect of Sp1 in OS." (PMID 32743904, 2020). "Additionally, the activation of TLR4/MyD88 results in Sp1 accumulation in cancer progression." (PMID 32144747, 2020). "Although, many studies reveal the vital role of CK2 in cancer cell proliferation and survival, and its activation is shown to inhibit the transcriptional activity of stimulatory protein-1 (SP-1) by suppressing its DNA binding activity through phosphorylation of the carboxy-terminal domain of SP-1." (PMID 32823607, 2020). "Notably, Sp1 is not only critical for efficient expression of many viral pathogens but also involved in cell differentiation, growth and apoptosis as well as immune responses and many types of cancers." (PMID 32760121, 2020). "NF-YAx readily competed with fully-spliced NF-YAl in CCAAT-box binding NF-Y complex formation but in contrast to NF-YAl and NF-YAs isoforms did not bind Sp1 and, therefore, represents a functional modifier of one of the more important physiological and cancer-associated transcription factors." (PMID 31805994, 2019). "Thus, blocking the interactions between KDM4A and some other proteins (such as pRb and SP1) may be a therapeutic strategy for some types of cancers." (PMID 29651880, 2018). "Interestingly, SP1 has been the target of miRNAs in many types of cancers." (PMID 29654167, 2018). "Lin28a, the transcriptional target of Sp-1, which couldfurther elevate the levels of certain cancer-related miRNAs, was also suppressed by urolithin A in HepG2.2.15 cells.Therefore, we speculated that suppression of Sp-1 could be responsible for thedecrease of Lin28a by urolithin A." (PMID 29742265, 2018). "Moreover, because of the crucial role of PDPK1 downstream PI3‐K/Akt pathway in cancer growth and progression 21, 40 and the reported links of this pathway in the regulation of SP1 and DNMT1 expressions in other studies 33, 38, 41, we also assessed the role of Akt signalling in this study." (PMID 28840963, 2018). "However, during the late stages, Sp1 expression varies in different cancer types." (PMID 28831131, 2017). "In cell culture models that use a TRF2 dominant negative mutant, Sp1 expression is down-regulated, leading to senescence phenotype, thereby highlighting the importance of this transcription factor in telomere biology and reiterating the possibility to target it in cancers that activate telomerase." (PMID 29045464, 2017). "As so many cancer-related genes including VEGF, E-cadherin, RECK, and integrin α5 can be regulated by Sp1, there may be other effector molecules implicated in AGEs/RAGE/Sp1 cascade which mediated gastric metastasis." (PMID 29262634, 2017). "However, the potential mechanism of Sp1 overexpression in cancer tissues is unclear now." (PMID 29262634, 2017). "Also, the downregulation of Sp1 has resulted in effective growth of cancer cells in nude mice." (PMID 28225083, 2017). "Several studies have shown that enhanced expression of Sp1 is correlated with angiogenic potential and poor prognosis in GC, whereas low expression of Sp1 has been reported to be involved in cancer progression and metastasis and may lead to poor prognosis in intestinal-type GC." (PMID 28117748, 2017). "Thus, miR-29c could serves as a tumor metastasis suppressor, which negatively controls the cancer metastasis via targeting many molecules including Sp1, GNA13, PTP4A, integrin β1 and MMP2." (PMID 27829234, 2016).